MSTN (myostatin)
Diseases named in the same sentence as MSTN in open-access papers (continued):
Sharing a sentence is not in itself a finding about the gene and the disease.
sarcopenia (continued). "Collectively, through the regulation of energy metabolism, the balance of muscle anabolism/catabolism, and the bone-muscle crosstalk network, Irisin and Myostatin play a central role in sarcopenia." (PMID 41209336, 2025). "Environmental factors such as chronic inflammation and metabolic disorders can activate the myostatin pathway, exacerbating the progression of sarcopenia." (PMID 41140691, 2025). "Research on animal models indicated myostatin as an aggravating factor in the development of sarcopenia and heart failure." (PMID 40943120, 2025). "Using myostatin and/or follistatin as sarcopenia biomarkers requires further knowledge of the way they evolve alongside muscle aging." (PMID 39585121, 2024). "It has been postulated that myostatin causing catabolism in males and reduced IGF-1 leading to anabolic decline in females have a role in the sex differences in sarcopenia development." (PMID 38285652, 2024). "We also observed that, similar to human fatty liver disease, obese mice show marked sarcopenia with increased Myostatin levels that are corrected in the liver-specific knockout of SPTBN1." (PMID 38323119, 2024). "Studies in humans have shown a relationship between high MSTN levels with sarcopenia and reduced survival rates in patients with cirrhosis." (PMID 38542721, 2024). "In patients with inflammatory bowel disease, serum myostatin levels correlate with sarcopenia severity." (PMID 39125931, 2024). "In the elderly with sarcopenia, muscle and serum myostatin levels are increased compared to younger individuals." (PMID 39125931, 2024). "Due to its implications in the human quality of life, most of the studies about sarcopenia and frailty with myostatin or follistatin have been developed in human serum/plasma." (PMID 39585121, 2024). "The available data on the relationship between MSTN level and the occurrence of sarcopenia are inconclusive." (PMID 38542721, 2024). "The authors showed that MSTN, together with albumin and creatine kinase, were complementary markers for the assessment of the presence of sarcopenia in these patients." (PMID 38542721, 2024). "In fact, the authors claim that myostatin can be a predictor of sarcopenia in all stages of cirrhosis." (PMID 38672282, 2024). "In the present study, the authors demonstrated the potential role of MSTN and Act A in the onset of sarcopenia, while also emphasizing the need to determine both markers." (PMID 38542721, 2024). "Myostatin (Mstn), a negative regulator of muscle growth, influences the proliferation and differentiation of muscle cells and contributes to sarcopenia." (PMID 39588187, 2024). "Myostatin is a myokine that inhibits protein synthesis and regeneration; sarcopenia results from an imbalance between protein synthesis and catabolism." (PMID 39337069, 2024). "The values of both myokines were found to be independent predictors of sarcopenia; however, those of myostatin were better correlated with the severity of liver disease." (PMID 38672282, 2024). "The backward deletion of non-significant variables allowed us to build a final model, which includes age, albumin, adiponectin, and myostatin concentrations as variables of interest in predicting sarcopenia." (PMID 39125361, 2024). "Myostatin, a TGF-β superfamily member expressed primarily in skeletal muscle, inhibits muscle growth and causes sarcopenia in cirrhosis." (PMID 38323119, 2024). "Myostatin increases in cases of sarcopenia mostly in females, while in males, it serves as a homeostatic regulator of muscle mass, suggesting sex differences in muscle physiology." (PMID 39851467, 2024). "Suggested potential sarcopenia biomarkers are myostatin (MSTN), insulin-like growth factor 1 (IGF-I), C-terminal agrin fragment (CAF), interleukin-6 (IL-6), tumor necrosis factor alpha (TNF-α), and vitamin D." (PMID 39769198, 2024).
sarcopenia (continued). "There are also studies that assess the relationship of MSTN with the occurrence of low muscle mass and sarcopenia in patients with cardiovascular diseases." (PMID 38542721, 2024). "Studies realized on aged human serums and our results on C2C12 murine cells show a similar tendency, where myostatin is downregulated and follistatin is upregulated in severe sarcopenia." (PMID 39585121, 2024). "The direction of the effect shows that higher age increases the likelihood of sarcopenia, while higher levels of albumin, adiponectin, and myostatin reduce its likelihood." (PMID 39125361, 2024). "We analyzed cellular morphological changes alongside the aging process, as well as the protein and gene expression of molecules related to sarcopenia, such as myostatin and follistatin." (PMID 39585121, 2024). "Modifications in mRNA levels of downstream genes of myostatin were also observed, highlighting the potential use of the method in the treatment of sarcopenia." (PMID 39409095, 2024). "Levels of MSTN (OR = 0.736, 95% CI 0.439–0.906; p = 0.0273) and Act A (OR = 0.665, 95% CI 0.379–0.974; p = 0.0229) were shown to be predictors of sarcopenia in the IBD patients after adjusting for age, gender, and BMI of the subjects." (PMID 38542721, 2024). "For example, a GWAS (genome‐wide association studies) study indicated that the gene‐coded myostatin (GDF8 gene, growth differentiation factor 8) is a shared mechanism in the pathogenesis of osteoporosis and sarcopenia." (PMID 38332659, 2024). "In this context, myostatin is considered a biomarker of SO, a combination of sarcopenia and obesity." (PMID 39562792, 2024). "The results of our study suggest that MSTN and Act A appear to be promising markers for the early diagnosis of an abnormal nutritional status and the presence of sarcopenia in IBD." (PMID 38542721, 2024). "For instance, the downregulated level of irisin and follistatin or the upregulation of activin A, TGF-β, and myostatin indicates a decrease in muscle mass and thus can serve as the biomarker for diagnosing sarcopenia." (PMID 37815907, 2024). "Increased myostatin levels also contribute to the development of sarcopenia, especially in the elderly, in people with cancer, in patients with sepsis, in patients treated in intensive care units, and in patients with chronic obstructive pulmonary disease." (PMID 38672190, 2024). "Chronic inflammation can accelerate protein breakdown and promotes sarcopenia by activating the ubiquitin-proteasome system, caspase 3, lysosome, and myostatin." (PMID 37252235, 2023). "Another study showed that higher serum myostatin levels were associated with sarcopenia in males, while in females, lower serum IGF1 levels were associated with sarcopenia." (PMID 36820956, 2023). "In COVID-19 patients, myostatin is a myokine related to glucose and lipid metabolic disturbances and acute sarcopenia onset among the infected elderly." (PMID 37408184, 2023). "Preclinical and clinical studies suggest the existence of a biological connection between IR, obesity and sarcopenia, mediated by the impaired function of the growth differentiation factor myostatin." (PMID 37358728, 2023). "In view of the importance of MSTN in regulating muscle homeostasis, the inhibitors targeting the MSTN signaling pathway have been developed for clinical use to improve patients with sarcopenia and muscular dystrophy." (PMID 37288303, 2023). "We conclude that serum myostatin was lower among excessive drinkers, among whom sarcopenia was observed in 57% of cases and reduced handgrip strength in 77% of cases." (PMID 36769301, 2023). "In another study, myostatin levels were lower in cirrhotic patients with sarcopenia and showed a direct (positive) correlation with SMI." (PMID 36769301, 2023). "While further research is needed, sarcopenia, or the age‐related loss of muscle mass, has been linked to myostatin levels, establishing LTBP4 as a potential therapy for sarcopenia." (PMID 37960979, 2023).
sarcopenia (continued). "Physiological aging is correlated with higher myostatin concentration, and myostatin inhibition has been applied in therapeutic treatment of sarcopenia." (PMID 37484967, 2023). "In our study, sarcopenia, assessed by multiple parameters, correlated with lower levels of myostatin, while the magnitude and range of circulating myostatin levels are similar to these data." (PMID 37554924, 2023). "The reduced capacity of the liver to detoxify ammonia elevates its concentrations which contributes to sarcopenia by interfering with the muscle protein synthesis pathways, that is, upregulating the myostatin secretion and stimulating muscle autophagy." (PMID 36620928, 2023). "In conclusion, ItP of myostatin inhibitory peptide is a potentially useful strategy for treating sarcopenia." (PMID 36986496, 2023). "The mechanism of action of myostatin inhibitors against sarcopenia involves their ability to inhibit myostatin activity in muscle tissue." (PMID 37371730, 2023). "Myostatin can induce oxidative stress and produce ROS in skeletal muscle cells, leading to muscle wasting during sarcopenia." (PMID 37153220, 2023). "In muscles, myostatin is correlated with developing new-onset acute sarcopenia in elderly COVID-19 patients." (PMID 37408184, 2023). "Sarcopenia has also been proposed as a potential mechanism; myostatin is a key factor inducing sarcopenia." (PMID 37554924, 2023). "have shown that the mRNA expressions of MSTN and BECN1 (autophagy associated proteins) were increased in skeletal muscle of patients with sarcopenia compared with controls." (PMID 37288303, 2023). "Taken together, our results suggest that ItP represents a novel intramuscular delivery strategy for medicines, including myostatin inhibitory peptides for the treatment of sarcopenia." (PMID 36986496, 2023). "Other studies have reported that IGF-1, myostatin, and insulin resistance were correlated with sarcopenia in elderly patients (both males and females) undergoing hemodialysis." (PMID 37764858, 2023). "Among the proteins considered as biomarkers of muscle atrophy and sarcopenia analyzed in this study—myostatin and CAF, only the latter substantially changed." (PMID 37237034, 2023). "The pathogenesis of sarcopenia includes systemic inflammation, myostatin signaling, and insulin resistance." (PMID 36983238, 2023). "Myokines such as irisin or myostatin are released from the skeletal muscle, and they play a role in the modulation of skeletal muscle homeostasis and by extension the development of sarcopenia and frailty." (PMID 36817773, 2023). "Sarcopenia in cirrhosis is thought to be mediated, in part, by myostatin, an autocrine inhibitor of skeletal muscle growth and development." (PMID 37554924, 2023). "In COVID-19 patients, myostatin-related new-onset sarcopenia happens due to the myostatin signaling that activates the phosphorylation of the SMAD proteins." (PMID 37408184, 2023). "Identifying possible and specific MSTN protein inhibitors is a viable approach for treating muscle disorders such as aging, muscular incapacity, sarcopenia, and sepsis." (PMID 35807547, 2022). "Among these, the expression pattern of myostatin appears to play a key role in both load-free muscle damage and the progression of age-related musculoskeletal disorders, such as osteoporosis and sarcopenia." (PMID 35185612, 2022). "There is evidence that human sarcopenia shows an increase in myostatin and a decrease in Akt phosphorylation efficiency." (PMID 35250869, 2022). "Mechanistically, sarcopenia develops as a result of protein energy malnutrition, a series of regulation among protein synthesis and breakdown, myostatin, reactive oxygen species and inflammatory cytokines." (PMID 35639492, 2022). "One attractive candidate to target sarcopenia is Myostatin (MSTN), a member of the transforming growth factor-beta (TGF-β) superfamily and a potent negative regulator of muscle growth and differentiation." (PMID 35954203, 2022).
sarcopenia (continued). "The proportion of patients with sarcopenia was higher in those with high IS levels but lower in those with high myostatin levels." (PMID 36287929, 2022). "Zinc supplementation in cirrhotic patients with sarcopenia is expected to improve sarcopenia, possibly by lowering myostatin in skeletal muscle from improved ammonia clearance." (PMID 36432541, 2022). "Conversely, Chew and colleagues, despite confirming the presence of such sex differences, showed that myostatin in men is a potential biomarker for coexistent sarcopenia and frailty in community-dwelling older adults." (PMID 36556504, 2022). "Hyperammonemia, which upregulates myostatin levels and activates autophagy, also plays a crucial role in the development of sarcopenia." (PMID 35771410, 2022). "Then, we examined the utility of myostatin in the diagnosis of sarcopenia, and the data showed that the AUC value of myostatin was the third highest (second to irisin and creatine kinase)." (PMID 35453410, 2022). "Myostatin (MSTN), a negative regulator of muscle mass, is reported to be increased in conditions linked with muscle atrophy, sarcopenia, and other muscle-related diseases." (PMID 35807547, 2022). "The proportion of patients with presarcopenia and sarcopenia was significantly lower in those with high myostatin levels than in those with low myostatin levels." (PMID 36287929, 2022). "Further studies are needed to identify the role of the myostatin/ASM ratio in the prediction of sarcopenia or physical performance in patients with CKD." (PMID 36287929, 2022). "For these reasons, myostatin has been investigated for its potential involvement in sarcopenia and frailty." (PMID 36556504, 2022). "Myostatin has emerged as a potential mediator of sarcopenia and is negatively related to muscle function and strength." (PMID 35287731, 2022). "The purpose of the study was to understand IGF-1, myostatin, and insulin resistance levels correlated with sarcopenia and the role of IGF-1, myostatin, and insulin resistance in the occurrence of sarcopenia in elderly patients undergoing HD." (PMID 35371569, 2022). "Among patients receiving HD, serum IGF-1 levels were found negatively correlated with sarcopenia, whereas myostatin levels correlated positively with sarcopenia." (PMID 35682722, 2022). "In the present study, we also measured the serum levels of IGF‐1 and myostatin as potential contributors to the development of sarcopenia." (PMID 35142082, 2022). "Being inversely proportional expressed to skeletal muscle mass in sarcopenia, myostatin promotes augmented muscle growth impairment and protein degradation more than in other individuals." (PMID 36362238, 2022). "The results suggested that IGF-1, myostatin, and insulin resistance were correlated with sarcopenia in elderly patients undergoing HD." (PMID 35371569, 2022). "The development of new drugs such as anti-myostatin antibodies to improve sarcopenia is also underway." (PMID 35160034, 2022). "In this study, we investigated the correlation between IGF-1 levels, myostatin levels, and insulin resistance and sarcopenia in elderly patients undergoing HD." (PMID 35371569, 2022). "Based on this recent study, IGF-1, myostatin, and insulin resistance were significantly correlated with sarcopenia in elderly patients undergoing hemodialysis." (PMID 35371569, 2022). "In this paper, we address the role of myostatin and follistatin as potential markers in the diagnosis of sarcopenia in patients with Crohn’s disease and ulcerative colitis, particularly in view of the genetic and biological aspects." (PMID 34680417, 2021). "These evidences also highlight a potential role of myostatin inhibition as therapeutic target to treat sarcopenia." (PMID 34858322, 2021). "A recent study revealed that BMPs directly compete with MSTN/activin/TGFβ in skeletal muscle, leading to increases in muscle mass, although their role in sarcopenia is not fully understood." (PMID 34943268, 2021).
sarcopenia (continued). "Our aim was to evaluate the factors related to sarcopenia and SO in T2DM patients and to explore its association with serum levels of myostatin and irisin." (PMID 34190188, 2021). "In previous animal studies, various forms of myostatin inhibition have shown to significantly increase muscle mass in pathophysiologic (i.e., cancer cachexia, Duchenne muscular dystrophy and sarcopenia) and normal mice models." (PMID 33947024, 2021). "We wanted to present the relationship between myostatin and sarcopenia and its components after adjusting the skeletal muscle mass (kg)." (PMID 34299795, 2021). "In the case of myostatin inhibition, this was tried on patients suffering from cachexia and sarcopenia, where the muscle function is unaffected by a genetic condition, without improving the muscle condition." (PMID 33802348, 2021). "On the other hand, myostatin blockade in the muscle of aged animals not only prevents sarcopenia but also increases insulin sensitivity." (PMID 34067004, 2021). "Compared to young adult muscle, myostatin expression is elevated in aged humans, potentially contributing to the progression of sarcopenia." (PMID 33418916, 2021). "The objective of this study was to identify the natural compounds that inhibit MSTN with therapeutic potential for the management of age-related disorders, specifically muscle atrophy and sarcopenia." (PMID 34500839, 2021). "Future studies are needed to elucidate the direct mechanism between FMOD and MSTN during human muscle aging for the management of sarcopenia." (PMID 34440852, 2021). "Sarcopenia—accelerated by upregulation of myostatin due to hyperammonaemia—becomes a predictor of morbidity and mortality, aggravated by obesity (sarcopenic obesity), and is difficult to treat." (PMID 34444908, 2021). "Further prospective studies are necessary to confirm the role of myostatin/ASM ratio for prediction of sarcopenia or physical performance." (PMID 34299795, 2021). "In the present study, we sought to identify the natural inhibitors of MSTN, with a view toward finding a novel means of managing age-related disorders and treating muscle atrophy and sarcopenia." (PMID 34500839, 2021). "Myostatin, a representative myokine related to sarcopenia, increased adipose tissue and suppressed adiponectin production as well as fatty acid oxidation in adipocytes." (PMID 33807573, 2021). "The analysis of molecular pathways of IBD-related sarcopenia assessed by using immunohistochemistry showed a down-expression of IGF1-R and Phospho-mTOR, markers of muscle growth, and an over-expression of Murf-1 and Myostatin, considered markers of sarcopenia." (PMID 34326845, 2021). "Previous studies demonstrated that in men, sarcopenia is induced by an increase in the catabolic hormone myostatin." (PMID 34411190, 2021). "Nevertheless, knowledge is still scarce about the roles of follistatin and myostatin in sarcopenia development among patients suffering from inflammatory bowel disease, which warrants further study." (PMID 34680417, 2021). "Various negative regulators (MSTN, atrogin-1, muscle ring finger-1, nuclear factor-kappaB (NF-B)) have been proposed to promote protein degradation during both sarcopenia and cachexia." (PMID 34500839, 2021). "The exact roles of serum myostatin as a biomarker of sarcopenia and its relationship with sarcopenia components (muscle mass and physical function) are uncertain, especially in the community-dwelling elderly." (PMID 34299795, 2021). "We also present data on new perspectives in the pharmacotherapy of sarcopenia (i.e., myostatin inhibitors and gene therapy)." (PMID 34680417, 2021). "Second, a prospective evaluation of the effect of establishing optimal glycemic control with diabetes treatment on the normalization of sarcopenia, irisin, and myostatin levels can be an important contribution." (PMID 34190188, 2021).